TSPYL5 (TSPY like 5)
Description:
Involved in modulation of cell growth and cellular response to gamma radiation probably via regulation of the Akt signaling pathway.
Synonyms: KIAA1750
Tractability: PROTAC: ubiquitination databases record sites on it; its protein half-life has been measured.
Gene: Protein-coding gene on chromosome 8 (97,273,488 to 97,277,928, reverse strand). Ensembl gene ENSG00000180543.
Subcellular location (Human Protein Atlas): Cytosol; Golgi apparatus
Gene Ontology:
Molecular function: protein binding
Biological process: cellular response to gamma radiation; positive regulation of cell population proliferation; positive regulation of phosphatidylinositol 3-kinase/protein kinase B signal transduction; positive regulation of protein ubiquitination; protein homooligomerization; nucleosome assembly
Cellular component: chromatin; nucleus
Genetic constraint (gnomAD): Missense variants: 320 observed, 254.46 expected, observed/expected ratio (o/e) 1.26, 90% interval 1.15 to 1.38. Synonymous variants: 166 observed, 116.83 expected, observed/expected ratio (o/e) 1.42, 90% interval 1.25 to 1.62.
Homologues: Orthologues: macaque TSPYL5 (99% identical), pig TSPYL5 (85% identical), rabbit TSPYL5 (82% identical), mouse Tspyl5 (72% identical), rat Tspyl5 (71% identical), dog TSPYL5 (63% identical), chimpanzee TSPYL5 (62% identical), zebrafish tspy (23% identical), Drosophila melanogaster Set (19% identical), Caenorhabditis elegans spr-2 (18% identical), Drosophila melanogaster Nap1 (12% identical), Caenorhabditis elegans nap-1 (11% identical), and 3 more. Paralogues in human: TSPYL4 (42% identical), TSPYL1 (39% identical), TSPYL6 (36% identical), TSPYL2 (34% identical), TSPY10 (23% identical), TSPY2 (23% identical), TSPY3 (23% identical), TSPY4 (23% identical), TSPY1 (23% identical), TSPY9 (23% identical), SETSIP (23% identical), TSPY8 (23% identical), and 6 more.
Diseases named in the same sentence as TSPYL5 in open-access papers:
TSPYL5 is named in the same sentence as 38 diseases in open-access papers, as found by Europe PMC text mining. Sharing a sentence is not in itself a finding about the gene and the disease. The quoted sentences say what the papers report.
breast carcinoma (10 papers, 2009 to 2023). "The dramatic down-regulation of TSPYL5 in the docetaxel-resistant breast cancer cells may be involved in the loss of docetaxel sensitivity." (PMID 30568280, 2018). "The expression of TSPYL5 can be used as a prognostic indicator for gastric cancer and breast cancer." (PMID 37760434, 2023). "The gene encoding the TSPYL5 protein is located on chromosome 8 (8q22.1, NCBI Gene ID: 85453) and is frequently amplified in breast cancer, which has led to considering TSPYL5 as an independent marker of poor prognosis in this type of cancer." (PMID 38203210, 2023). "The overexpression of RGS2 in breast cancer cells reduces the protein level of testicular specific Y-like protein 5 (TSPYL5) to disturb calcium pumps, thereby inhibiting cellular proliferation." (PMID 33500709, 2021). "TSPYL5 is a well-known prognostic factor of poor outcome in breast cancer patients." (PMID 32631280, 2020). "Previous studies indicated that TSPYL5 could be an independent marker of poor outcome in breast cancer based on their high expression in aggressive basal-like breast cancers." (PMID 28235398, 2017). "TSPYL5 has been previously used as a prognostic biomarker in breast cancer." (PMID 24073403, 2013). "Furthermore, identified six genes (TSPYL5, CD55, CCNE2, DCK, BBC3, and MUC1) susceptible to breast cancer were verified through the literature mining, GO analysis, and pathway functional enrichment analysis." (PMID 24073403, 2013). "Using netSAM, we identified six novel genes (TSPYL5, CD55, CCNE2, DCK, BBC3, and MUC1) as cancer biomarkers for predicting survival and metastasis in patients with breast cancer." (PMID 24073403, 2013). "Among these oncogenes, TSPYL5 and CCNE2 have been already known as prognostic biomarkers in breast cancer, CD55 has been suspected of playing an important role in breast cancer prognosis from literature evidence, and other three genes are newly discovered breast cancer biomarkers." (PMID 24073403, 2013).
gastric cancer (8 papers, 2010 to 2023). A primary or metastatic malignant neoplasm involving the stomach. "TSPYL5 repression via DNA methylation is frequently associated with cancer, including endometrioid endometrial adenocarcinoma, malignant glioma, gastric cancer, prostate cancer, and HCC." (PMID 37760434, 2023). "Some studies suggest that the methylation of the tumor-suppressor gene TSPYL5 will cause its expression silencing and, thereby, gastric cancer." (PMID 33490103, 2020). "Yet another example is provided by TSPYL5 (encoding testis-specific Y-like protein), which is a potent tumor suppressor gene and a frequent target of epigenetic silencing in glial tumors and gastric cancers." (PMID 21156036, 2010). "Methylation induced TSPYL5 gene silencing was previously reported in glioma and gastric cancer types." (PMID 28235398, 2017). "The TSPYL5 gene is of particular interest because, apart from the documented role as a putative TSG in glioblastoma and gastric cancer, it has been implicated in cancer signaling pathways involving CDKN1A (p21, WAF1/Cip 1) and pAKT in lung carcinoma cells." (PMID 28235398, 2017). "The methylation silencing of TSPYL5 has been reported in esophageal cancers, gastric cancers and malignant gliomas, and TSPYL5 has been suggested to be a tumor suppressor gene." (PMID 27255271, 2016). "In primary gastric cancer, methylation-specific PCR of TSPYL5 has revealed hypermethylation at the CpG island in 23 out of the 36 (63.9%) cases." (PMID 25997695, 2015). "The mRNA expression of TSPYL5 is frequently downregulated and inversely correlates with DNA methylation in seven out of nine gastric cancer cell lines." (PMID 25997695, 2015). "Out of the 10 hypermethylated genes, we focused on TSPYL5 since it was shown to be hypermethylated in various types of cancers including glioma, glioblastoma, astrocytomas, gastric cancer, esophageal squamous cell carcinomas, hepatocellular carcinoma and endometrial cancer." (PMID 28837588, 2017). "Interestingly, the TSPYL5 gene has been reported to suppress gastric cancer development." (PMID 27458158, 2016).
lung carcinoma (8 papers, 2017 to 2025). "TSPYL5 has been implicated in cancer cell proliferation by activating Akt signaling and has been implicated in the radiation resistance of lung cancer cells." (PMID 36552994, 2022). "MUC16 performs a meaningful function in metastasis and tumourigenesis in lung cancer by regulating TSPYL5 through JAK2/STAT3/GR." (PMID 36059804, 2022). "Treatment with the TS120-T peptides in other lung cancer cells with high levels of TSPYL5, such as H358 and H2009, also inhibited cell growth and enhanced the sensitivity of the cells to γ-radiation and gefitinib." (PMID 34163000, 2021). "It has been reported that in lung carcinoma cells, TSPYL5 was able to suppress CDKN1A by modulating PTEN/AKT pathway." (PMID 28235398, 2017). "Previous studies have shown a correlation between methylation in chromosome 8 region (Chr 8: 97278129–97278175) and loss of TSPYL5 gene expression in lung carcinoma cells, although, no tissue studies or normal cell studies have been done." (PMID 28235398, 2017). "We have studied TSPYL5 as CSC-associated factor mainly in lung CSCs; however, its expression is not restricted to lung cancer." (PMID 34163000, 2021). "However, in contrast to lung carcinoma cells LNCaP cells lack PTEN, so any involvement of TSPYL5 in modulating CDKN1A must work by a PTEN-independent mechanism." (PMID 28235398, 2017).
prostate carcinoma (7 papers, 2017 to 2025). A carcinoma that arises from epithelial cells of the prostate gland. "The overexpression of TSPYL5 has also been linked to chemotherapy sensitivity in both lung and prostate cancer cells." (PMID 30568280, 2018). "Further TSPYL5 gene and protein expression in prostate carcinoma cells and diseased tissues including its susceptibility for epigenetic silencing is unknown." (PMID 28235398, 2017). "In prostate cancer it’s been recently proven that miR-483–5p antagonization through the long non-coding RNA LINC00908 lead to an upregulation of TSPYL5, inhibiting prostate cancer progression." (PMID 35186042, 2022). "Linc00908 sponges with miR-483-5p in prostate cancer, and competitively reduces miR-483-5p targeting to TSPYL5 (testis-specific Y-encoded-like protein 5) to exert its anticancer function." (PMID 33088214, 2020). "To gain insight into the role of TSPYL5 in prostate cancer, we investigated its expression, methylation pattern, its role in signaling pathways and drug sensitivity and presence of its protein with respect to disease severity." (PMID 28235398, 2017). "Therefore, it is not excluded that an unnoticed molecular plays a similar role to TSPYL5 in the nuclear membrane translocation of G3BP2 in prostate cancer cells." (PMID 40319028, 2025). "The chromosomal location of the TSPYL5 gene is 8Q22.1, and its exact role in prostate cancer etiology remains unclear." (PMID 28235398, 2017). "In conclusion, our studies demonstrate the potential significance of TSPYL5 in prostate carcinoma and that it could have more than one function depending on the cellular phenotype." (PMID 28235398, 2017). "Altogether, TSPYL5 expression diminishes in high grade prostate carcinoma compared to the benign tissue or intermediate grade prostate carcinoma suggesting that TSPYL5 could function as an indicator of disease progression." (PMID 28235398, 2017). "Reduced gene product in high GS tumors suggests that TSPYL5 could likely function as an indicator of more advanced prostate carcinoma." (PMID 28235398, 2017). "Treatment of prostate carcinoma cells in which TSPYL5 was absent or low (DU145 and LNCaP) with the demethylating agent 5-aza-2′-deoxycytidine upregulated its expression in these cells." (PMID 28235398, 2017). "Taken together, these data suggest that the absence of TSPYL5 may be an indicator of more advanced prostate cancer disease." (PMID 28235398, 2017). "Also, not known is the variation in TSPYL5 protein expression with regards to progression of prostatic carcinoma and its possible role in drug sensitivity." (PMID 28235398, 2017). "TSPYL5 was differentially expressed in non-tumorigenic prostate epithelial cells (RWPE-1), androgen independent (DU145), dependent (LNCaP) prostate carcinoma cells and tissues." (PMID 28235398, 2017).
Cirrhosis (3 papers, 2023 to 2025). A chronic disorder of the liver in which liver tissue becomes scarred and is partially replaced by regenerative nodules and fibrotic tissue resulting in loss of liver function. "AK055957 and TSPYL5 exhibited higher DNA methylation levels in cirrhotic HCC compared to cirrhosis (p < 0.05)." (PMID 37835478, 2023). "In summary, the data from MeD-seq confirmed the results of qMSP that non-cirrhotic HCC had the highest methylation levels of HOXA1, CLEC11A, and TSPYL5 compared to hepatitis, benign lesions, and cirrhosis." (PMID 37835478, 2023). "In summary, we found that patients with non-cirrhotic HCC exhibited aberrant DNA methylation levels in liver tissue for HOXA1, CLEC11A, AK055957, and TSPYL5 as compared to hepatitis, benign lesions, and cirrhosis." (PMID 37835478, 2023). "The results demonstrate that gender and cirrhosis status are important clinical risk factors for the hypermethylation of HOXA1 and TSPYL5, respectively." (PMID 37835478, 2023). "Notably, the median methylation scores of HOXA1, CLEC11A, and TSPYL5 were higher in cirrhotic HCC compared to cirrhosis, hepatitis, and benign lesions, although only CLEC11A exhibited a statistical difference (p < 0.05)." (PMID 37835478, 2023). "However, using MeD-seq, TSPYL5 was unable to distinguish cirrhotic HCC from cirrhosis or hepatitis, while CLEC11A was, which differed from the qMSP data." (PMID 37835478, 2023). "Hypermethylation of HOXA1, CLEC11A, AK055957, and TSPYL5 was observed in non-cirrhotic HCC compared to hepatitis and cirrhosis (p < 0.05)." (PMID 37835478, 2023).
glioma (3 papers, 2010 to 2017). A benign or malignant brain and spinal cord tumor that arises from glial cells (astrocytes, oligodendrocytes, ependymal cells). "Furthermore, re-expression of TSPYL5 in glioma and gastric cell lines, in which the endogenous TSPYL5 promoter was shown to be methylated, suppressed cell growth in culture." (PMID 28837588, 2017).
ovarian carcinoma (3 papers, 2020 to 2022). A malignant neoplasm originating from the surface ovarian epithelium. "miR-629 overexpression has also shown the ability to promote proliferation, migration and invasion in ovarian cancer by directly inhibiting TSPYL5." (PMID 35186042, 2022). "Similarly, previous research has demonstrated that decreasing TSPYL5 expression may influence ovarian cancer cell invasion and proliferation in a suppressive way." (PMID 31938018, 2020).
breast tumor (1 paper, 2021). "The TSPYL5 was detected in 21–27% of primary breast tumor samples and is associated with a higher propensity of metastatic recurrence." (PMID 33670062, 2021).
Cognitive impairment (1 paper, 2025). Abnormal cognition is characterized by deficits in thinking, reasoning, or remembering. "Support for a potential relevance of antibodies against SRRM3 and TSPYL5 proteins comes from the observed association between their levels and cognitive impairment, and between TSPYL5 and muscle pain, in piME/CFS patients." (PMID 41050647, 2025). "This raises the possibility that the observed association of TSPYL5 autoantibodies with cognitive impairment, headache, and muscle pain in piME/CFS may be due to a potentially inhibitory effect on angiogenesis." (PMID 41050647, 2025). "However, in the piME/CFS group, significant positive correlations were found between autoantibodies to SRRM3 protein and cognitive impairment, and between antibodies to TSPYL5 protein and both cognition and muscle pain." (PMID 41050647, 2025).
colorectal cancer (1 paper, 2025). A primary or metastatic malignant neoplasm that affects the colon or rectum.
germ cell tumor (1 paper, 2017). A benign or malignant, gonadal or extragonadal neoplasm that originates from germ cells. "Lastly, we asked whether TSPYL5 silencing also occurs in germ cell tumors (GCT), which are tumors of germ cells origin that initiate from primordial germ cells at different developmental stages." (PMID 28837588, 2017).
leiomyosarcoma (1 paper, 2021). An uncommon, aggressive malignant smooth muscle neoplasm, usually occurring in post-menopausal women. "Hypermethylation in the potassium voltage-gated channel, Isk-related family, member 3 (KCNE3), TSPY-like 5 (TSPYL5), Homeobox A11 (HOXA11), HOXA11 antisense RNA (HOXA11AS), HOX9, and LOC100130872, was observed in leiomyosarcoma." (PMID 35008848, 2021).
liver cancer (1 paper, 2021). An epithelial or non-epithelial malignant neoplasm that arises from the liver. "TSPYL5 has been confirmed as a cancer stemness factor also in other types of cancer, including liver cancer and pancreatic cancer, thus warranting further studies on TSPYL5 and AKT activation in other tumors." (PMID 34163000, 2021).
neuroblastoma (1 paper, 2025). Neuroblastoma (NB) is the most common solid, extracranial childhood tumor. "With this signal pathway, TSPYL5 augments the malignant characteristics of neuroblastoma cells." (PMID 40319028, 2025). "Firstly, we could not obtain the fresh neuroblastoma tissues in which to investigate the nuclear periphery location of G3BP1 and its interaction with TSPYL5." (PMID 40319028, 2025).
non-small cell lung carcinoma (1 paper, 2021). A group of at least three distinct histological types of lung cancer, including non-small cell squamous cell carcinoma, adenocarcinoma, and large cell carcinoma. "Here, we identify testis-specific Y-like protein 5 (TSPYL5) as an upstream regulator of CSC-associated genes in non-small cell lung cancer cells, and suggest as a therapeutic target for CSC elimination." (PMID 34163000, 2021).
Obesity (1 paper, 2015). Accumulation of substantial excess body fat. "They include the locus RBMS1-TANK (men, Pdifflean-overweight= 4.7 x 10-8), a region that has been associated with several obesity related traits, and TSPYL5 (men, Pdifflean-overweight= 9.1 x 10-8), regulating adipocytes-produced estradiol." (PMID 25811787, 2015).
prostate tumors (1 paper, 2017). "TSPYL5 protein expression in benign and diseased prostate tumor tissues was performed by immunohistochemistry and in the cells by Western blotting." (PMID 28235398, 2017). "In this study we report that TSPYL5 gene and protein expression varied in prostate adenocarcinoma (PC) cells and human benign and prostate tumor tissues as analyzed by qRT-PCR and immunoblotting." (PMID 28235398, 2017). "After identifying an inverse relationship between TSPYL5 mRNA and the presence of methylation in NT and PC cells, we sought to extend the analysis of gene expression and DNA methylation to benign and prostate tumor tissues." (PMID 28235398, 2017). "Such a difference in TSPYL5 expression could be exploited to identify the clinical behavior of intermediate grade prostate tumors (GS-7)." (PMID 28235398, 2017). "It is hypothesized that more advanced prostate tumors will have low TSPYL5 gene and protein expression compared to moderately advanced or normal phenotype, and such differential expression of TSPYL5 is due to epigenetic modulation of this gene." (PMID 28235398, 2017). "However, to classify GS-7 patients based on diminished TSPYL5, large cohorts of prostate tumor samples will need to be investigated." (PMID 28235398, 2017). "Decrease in TSPYL5 protein in advanced tumors might possibly function as an indicator of prostate tumor progression." (PMID 28235398, 2017). "TSPYL5, DNMT-1 and DNMT-B gene expression in DU145, LNCaP and RWPE-1 cells and prostate tumor tissues was analyzed by qRT-PCR and RT-PCR." (PMID 28235398, 2017).